CENPM (centromere protein M)
Diseases named in the same sentence as CENPM in open-access papers (continued):
Sharing a sentence is not in itself a finding about the gene and the disease.
tumor (13 papers, 2019 to 2025). "Studies also found the CENPM genes encode a human minor histocompatibility antigen expressed by tumor cells." (PMID 32863765, 2020). "Moreover, CENPM can encode a human minor histocompatibility antigen expressed by tumor cells, it had reported that CENPM had an association with tumor progression." (PMID 31703591, 2019). "The upregulation of CENPM in ccRCC predicts a poor clinical outcome, and this malignant phenotype may be associated with its exacerbation of the immunosuppressive state in the tumor microenvironment." (PMID 36635779, 2023). "The anti-tumor effects of CENPM knockdown were reversed by cGAS inhibition, confirming cGAS-STING involvement." (PMID 39949780, 2025). "To further characterize the effect of CENPM on c-MYC HCC tumor development, we silenced CENPM in human HCC cell lines using siRNA (siCENPM)." (PMID 39325536, 2024). "Increased CENPM levels were observed to enhance the accumulation of Tregs and Th2 cells within the tumor, while simultaneously inhibiting CD8 + T cells and Mast cells." (PMID 38200449, 2024). "Analysis in the weight subgroup; gender subgroup; ethnicity subgroup; tumor grade subgroups analysis also showed significantly higher CENPM in HCC patients." (PMID 32863765, 2020). "The expression of CENPM from GEO database was significantly up-regulated in tumor group compared with normal group." (PMID 31703591, 2019). "This evidence predicts that CENPM may act synergistically with immune checkpoints to exacerbate the immunosuppressive state in the tumor microenvironment." (PMID 36635779, 2023). "CENPM was highly expressed in tumor tissues, while DLC-1 was significantly downregulated in HCC." (PMID 33591950, 2021). "Then, we focused on CENPM due to its important functions during tumor progression." (PMID 34513693, 2021). "Then 68 paired HCC samples and matching adjacent non-tumor tissues obtained from Zhongnan Hospital of Wuhan University were used for examining the mRNA level of CENPM via qRT-PCR, and the results were consistent with GEO databases and TCGA data analysis, and also confirmed by western blotting." (PMID 31703591, 2019). "Additionally, we established xenograft model and orthotopic HCC mouse model to further verify that CENPM promoted tumor growth." (PMID 31703591, 2019). "Then we further established an orthotopic transplantation tumor model of HCC in nude mice to confirm oncogenic role of CENPM, and after 6 weeks, PET/CT operated by Union Hospital PET Center of Tongji Medical College (Wuhan, China) was used for the measurement of liver lesions." (PMID 31703591, 2019). "We first checked the mRNA level of CENPM in 24 kinds of tumor types from TCGA to figure out the CENPM whether was a oncogene or a tumor suppressor, and found that the expression of CENPM was almost higher in tumor group than corresponding normal group." (PMID 31703591, 2019). "Finally, a comprehensive analysis of the crosstalk between CENPM and immune features in the tumor microenvironment was performed based on the ssGSEA algorithm, the tumor immune dysfunction and exclusion (TIDE) algorithm, the TIMER2.0 database and the TISIDB database." (PMID 36635779, 2023). "Besides, the expression of CENPM was closely related to tumor grades of HCC." (PMID 31703591, 2019). "Knockdown of CENPM also resulted in a decrease of ki67 positive cells and a decline of FGL1 levels, as shown by ki67 staining and immunofluorescence of ACC metastatic tumour nodules, respectively." (PMID 39778025, 2025). "Reducing CENPM expression in ovarian cancer (OC) cells activates the cGAS-STING pathway, suppressing tumor growth and spread by inducing pyroptosis, an inflammatory cell death." (PMID 39949780, 2025). "Overexpression of MDK, CENPM, and SSR2 promotes tumor metastasis, angiogenesis, and tumorigenesis, leading to poor prognosis in patients with HCC." (PMID 34900444, 2021).
tumor (continued). "In this study, we first explored mRNA and protein levels of CENPM in HCC samples, matching adjacent non-tumor tissues and six hepatoma cell lines by polymerase chain reaction (PCR), western blotting and immunohistochemistry (IHC)." (PMID 31703591, 2019). "In contrast, genes related to tumor metastasis, such as SPP1 and CENPM, were up-regulated in MM." (PMID 37880239, 2023). "In addition, we also analyzed the connection between CENPM expression and clinical features as well as the correlation of its expression with immune infiltration level in HCC comes an online tumor infiltrating immune cells analysis tool." (PMID 32863765, 2020).
CENPM also shares sentences with these, for which no sentence is quoted: ovarian carcinoma (3 papers); melanoma (2); adrenocortical carcinoma (1); cervical cancer (1); clear cell renal cell carcinoma (1); kidney cancer (1); lung carcinoma (1); schizophrenia (1); tongue cancer (1).